GLG1 (golgi glycoprotein 1)
Description:
Binds fibroblast growth factor and E-selectin (cell-adhesion lectin on endothelial cells mediating the binding of neutrophils).
Synonyms: ESL-1; MG160; MG-160; CFR-1
Tractability: Antibody: its Gene Ontology location is reachable by antibodies, with high confidence; UniProt predicts a signal peptide or a membrane-spanning region. PROTAC: ubiquitination databases record sites on it; its protein half-life has been measured.
Gene: Protein-coding gene on chromosome 16 (74,447,427 to 74,607,144, reverse strand). Ensembl gene ENSG00000090863.
Subcellular location: Golgi apparatus membrane; Golgi outpost; Cytoplasm, cytoskeleton, microtubule organizing center
Subcellular location (Human Protein Atlas): Golgi apparatus; End piece; Mid piece; Principal piece
Pathways (Reactome):
Hemostasis: Cell surface interactions at the vascular wall
Gene Ontology:
Molecular function: fibroblast growth factor binding; signaling receptor binding
Biological process: regulation of transforming growth factor beta receptor signaling pathway
Cellular component: extracellular exosome; Golgi apparatus; Golgi membrane; membrane; plasma membrane; postsynaptic Golgi apparatus; extracellular matrix; microtubule organizing center
Genetic constraint (gnomAD): Loss-of-function variants: 19 observed, 64.26 expected, observed/expected ratio (o/e) 0.3, 90% interval 0.2 to 0.43. The synonymous counts are far from expectation, so gnomAD's model fits this gene poorly and the ratio says little. Missense variants: 756 observed, 824.21 expected, observed/expected ratio (o/e) 0.92, 90% interval 0.86 to 0.97. Synonymous variants: 392 observed, 310.33 expected, observed/expected ratio (o/e) 1.26, 90% interval 1.16 to 1.37.
Homologues: Orthologues: chimpanzee GLG1 (99% identical), macaque GLG1 (99% identical), rabbit GLG1 (97% identical), pig GLG1 (97% identical), guinea pig GLG1 (97% identical), mouse Glg1 (96% identical), rat Glg1 (96% identical), dog GLG1 (94% identical), tropical clawed frog glg1 (80% identical), zebrafish glg1a (75% identical), Drosophila melanogaster Glg1 (32% identical), zebrafish glg1b (32% identical), and 1 more.
Diseases named in the same sentence as GLG1 in open-access papers:
GLG1 is named in the same sentence as 34 diseases in open-access papers, as found by Europe PMC text mining. Sharing a sentence is not in itself a finding about the gene and the disease. The quoted sentences say what the papers report.
Ewing sarcoma (6 papers, 2018 to 2025). A small round cell tumor that lacks morphologic, immunohistochemical, and electron microscopic evidence of neuroectodermal differentiation. "Collectively, we propose utilizing BCL11B and GLG1 as novel biomarkers for the diagnosis of Ewing sarcoma and recommend validating their diagnostic value in a prospective and multi-centered setting." (PMID 29416716, 2018). "Based on previous reports, GLG1 can be used as an auxiliary marker for the diagnosis of Ewing sarcoma by immunohistochemistry." (PMID 36619306, 2022). "In the current study, comparative expression analyses revealed that ATP1A1, BCL11B, and GLG1 constitute potential specific markers for Ewing sarcoma." (PMID 29416716, 2018). "Automated cut-off-finding and combination-testing in a tissue-microarray comprising 174 samples demonstrated that detection of high BCL11B and/or GLG1 expression is sufficient to reach 96% specificity for Ewing sarcoma." (PMID 29416716, 2018). "While CD99 showed broad expression in many different tumor entities, ATP1A1, BCL11B, and GLG1 were only expressed at low levels in every tumor entity relative to Ewing sarcoma, indicating a higher specificity for this disease than CD99." (PMID 29416716, 2018). "In fact, detecting high BCL11B and/or GLG1 expression in CD99-high tumors reached a specificity for Ewing sarcoma of at least 96%, and of 99% if both markers were highly expressed (defined as IRS > 9)." (PMID 29416716, 2018). "Since high expression of BCL11B and/or GLG1 (defined as IRS > 9) was found in 79% of all Ewing Sarcoma cases and associated with a specificity of 96%, diagnosis of Ewing sarcoma should be strongly considered if one or both markers are highly expressed." (PMID 29416716, 2018). "To explore the potential of ATP1A1, BCL11B, GLG1, and CD99 as prognostic biomarkers, we analyzed the association of their expression levels with outcome in a large cohort of Ewing sarcoma patients (n = 166)." (PMID 29416716, 2018). "Collectively, we show that ATP1A1, BCL11B, and GLG1 are EWSR1-FLI1 targets, of which BCL11B and GLG1 offer a fast, simple, and cost-efficient way to diagnose Ewing sarcoma by immunohistochemistry." (PMID 29416716, 2018). "To offer a simple, fast, and cost-effective way to reliably diagnose Ewing sarcoma by IHC, we combined in silico, in vitro, and in situ analyses, and found that the high expression of BCL11B and/or GLG1 is nearly diagnostic for this disease." (PMID 29416716, 2018). "Based on the results, cg00982952 showed importance for Ewing (Ewing sarcoma) classification in all classifiers, and this methylation site could be annotated to the gene GLG1." (PMID 36619306, 2022). "Specific immunohistochemical staining of these proteins in comprehensive tissue microarrays (TMAs) combined with automated cut-off determination and combination-testing demonstrated that detecting high BCL11B and/or GLG1 levels is sufficient to reach 96% specificity for Ewing sarcoma." (PMID 29416716, 2018). "In addition to these findings in vitro, gene-set enrichment analyses of either ATP1A1-, BCL11B-, or GLG1-correlated genes within 166 primary Ewing sarcoma tumors revealed that the most significantly (min." (PMID 29416716, 2018). "Collectively, our data provide evidence that fast and robust diagnosis of Ewing sarcoma is enabled by immunohistochemical detection of the super-enhancer-driven EWSR1-ETS targets BCL11B and GLG1." (PMID 29416716, 2018). "Although the detailed mechanism between GLG1 and Ewing sarcoma formation has not been clearly studied, the researchers found that GLG1 may be involved in the progression of multiple tumors by affecting the transport of key molecules involved in cell migration." (PMID 36619306, 2022). "Further analyses indicated that while ATP1A1 exhibited high specificity (90%), it had no additional value for establishing Ewing sarcoma diagnosis if it was combined with BCL11B and GLG1." (PMID 29416716, 2018).
prostate carcinoma (5 papers, 2014 to 2025). A carcinoma that arises from epithelial cells of the prostate gland. "Recent research has identified ESLs expressed by prostate cancer cells, such as CD44 and Golgi glycoprotein 1 (GLG1)." (PMID 39944529, 2025).
rhabdomyosarcoma (2 papers, 2018 to 2020). A rare aggressive malignant mesenchymal neoplasm arising from skeletal muscle. "In fact, ATP1A1 and GLG1 were previously shown to be upregulated after ectopic expression of EWSR1-FLI1 in the rhabdomyosarcoma cell line RD." (PMID 29416716, 2018). "In the current study, we confirmed the high specificity of BCL11B and GLG1 for EwS in a far larger and independent cohort of 133 EwS and 320 non-EwS from 11 differential diagnoses, including 118 samples from close morphological mimics such as DSRCT, neuroblastoma, and rhabdomyosarcoma." (PMID 32164354, 2020).
sarcoma (2 papers, 2018 to 2020). A usually aggressive malignant neoplasm of the soft tissue or bone. "While 88% of tested Ewing-like sarcomas displayed strong CD99-immunoreactivity, none displayed combined strong BCL11B- and GLG1-immunoreactivity." (PMID 29416716, 2018). "Interestingly, the tested series of PDX models included five samples from so-called ‘Ewing-like’ sarcomas (3 CIC-DUX4-positive sarcomas and 2 BCOR-rearranged sarcomas), which did not exhibit any BCL11B and GLG1 immunoreactivity." (PMID 32164354, 2020).
B-cell lymphoma (1 paper, 2020). "Using comparative transcriptomics in EwS and 20 morphological mimics, we previously identified the proteins BCL11B (B-cell lymphoma/leukemia 11B) and GLG1 (Golgi apparatus protein 1) as potential auxiliary markers that can support the diagnosis of EwS." (PMID 32164354, 2020).
bladder cancer (1 paper, 2015). "GLG1 has been shown by immunohistochemistry to be highly or intermediately expressed in both high and low grade urothelial cancer tissue samples; furthermore, GLG1 was detected on the cell surface of bladder cancer cell lines (Ward, unpublished data)." (PMID 28248271, 2015).
brain tumors (1 paper, 2014). "GLG1 was concluded to be associated with the tumorigenesis of some carcinomas and malignancy of brain tumors." (PMID 25379943, 2014).
endothelial dysfunction (1 paper, 2022). In vascular diseases, endothelial dysfunction is a systemic pathological state of the endothelium (the inner lining of blood vessels) and can be broadly defined as an imbalance between vasodilating and vasoconstricting substances produced by (or acting on) the endothelium. "scRNA-seq was applied in this study and the analysis proved that GLG1 expressed in mesangial cells, principal cells and proximal tubular cells, interacting with SELE in endothelial dysfunction." (PMID 35935760, 2022).
inflammatory bowel disease (1 paper, 2023). A spectrum of small and large bowel inflammatory diseases of unknown etiology. "In another research, engineered GLG1(Golgi glycoprotein 1)-exosomes carrying Wnt agonist 1 proved to alleviate impaired bone loss and bone fracture caused by inflammatory bowel diseases." (PMID 37620914, 2023).
Intellectual disability (1 paper, 2025). "Associations with intellectual disability include rs78294462 in TCF4, rs376456 and rs1009136 in MAU2, and rs7200247 in GLG1." (PMID 40282399, 2025).
lung carcinoma (1 paper, 2022). "Circ_GLG1/miR-622, circFNTA/miR-370-3p and circ-MEMO1/miR-101-3p axes have been shown to regulate expression of KRAS in colorectal, bladder and lung cancer cells." (PMID 35139853, 2022).
triple-negative breast carcinoma (1 paper, 2022). An invasive breast carcinoma which is negative for expression of estrogen receptor (ER), progesterone receptor (PR), and human epidermal growth factor receptor 2 (HER2). "GLG1 has been postulated as an important regulator of membrane trafficking and described to be instrumental for metastatic colonization in bone of BM2 myeloid cells and M1a cells (derivative from the SUM159 triple negative breast cancer cell line) by binding E-selectin." (PMID 35159257, 2022).
tumor (10 papers, 2015 to 2025). "These are suggestive of the tumor suppressive role of GLG1, which has been confirmed by its clinical association." (PMID 35582416, 2022). "For non-EwS cases, the proposed marker combination of CD99, BCL11B, and GLG1 yielded a consistent classification over all 3 cores taken from different areas of each tumor sample in 95.2%." (PMID 32164354, 2020). "Therefore, the heterogeneity of scoring for CD99, BCL11B, and GLG1 in different cores per sample, originating from different regions of a given tumor block, was assessed." (PMID 32164354, 2020). "Therefore, it seems plausible that the GLG1 detected in pTa patient urine is tumour derived." (PMID 28248271, 2015). "While its tumor-suppressive effect has been attributed to the blockage of the NMDA-receptor, another mechanism was recently proposed involving the Golgi glycoprotein 1 (GLG1), an intracellular fibroblast growth factor receptor (FGFR)." (PMID 38275722, 2023). "For CD99, 81% of non-EwS tumor samples were classified consistently across all three cores per sample, for BCL11B 97.6%, and for GLG1 and 94.8%, indicating only little intra-tumoral heterogeneity in EwS differential diagnoses." (PMID 32164354, 2020).
cancer (5 papers, 2014 to 2021). A tumor composed of atypical neoplastic, often pleomorphic cells that invade other tissues. "ESL-1, one of E-selectin ligand, is a Ca2+ dependent inducible cell adhesion glycoprotein and is encoded by a single gene locus named Glg1 (Golgi-complex-localized glycoprotein-1), but its roles in cancer metastasis are not well known." (PMID 25301730, 2014). "As observed in this study, GLG1 was concluded to be significantly associated with T category cancer with regards to invasion depth." (PMID 25379943, 2014). "In agreement with similar findings on different markers in other cancer entities, ATP1A1 and GLG1 may have diagnostic as well as prognostic utility." (PMID 29416716, 2018).
infection (1 paper, 2018). The state of being infected such as from the introduction of a foreign agent such as serum, vaccine, antigenic substance or organism. "For example, a significant difference was observed between HCMV and mock infection within 4 hr for HLTF, DAXX, and GLG1." (PMID 30122656, 2018).
GLG1 also shares sentences with these, for which no sentence is quoted: gastric cancer (2 papers); atherosclerosis (1); B-cell CLL (1); breast carcinoma (1); chronic myeloid leukemia (1); colorectal cancer (1); hepatocellular carcinoma (1); lupus nephritis (1); metastatic prostate carcinoma (1); myeloma (1); neuroblastoma (1); Osteopenia (1); osteopetrosis (1); osteosarcoma (1); prostate tumors (1); renal failure (1); schizophrenia (1); septicemia (1); vasculitis (1).